NDUFS2 (NADH:ubiquinone oxidoreductase core subunit S2)
Diseases named in the same sentence as NDUFS2 in open-access papers (continued):
Sharing a sentence is not in itself a finding about the gene and the disease.
triple-negative breast carcinoma (1 paper, 2022). An invasive breast carcinoma which is negative for expression of estrogen receptor (ER), progesterone receptor (PR), and human epidermal growth factor receptor 2 (HER2). "A recent study found that SMIP004-7 could inhibit the growth of triple-negative breast cancer by engaging NDUFS2, which is also located in Complex I." (PMID 36119539, 2022).
cancer (12 papers, 2014 to 2026). A tumor composed of atypical neoplastic, often pleomorphic cells that invade other tissues. "The results showed that the HIV peptides with the highest homology to TAAs identified in breast (CCR9), colon (EPCAM, GLOD5, CEACAM8) as well as prostate (NDUFS2) cancer and linked to most frequent HLA alleles (01:01; 02:01 and 24:02), are highly conserved across HIV isolates." (PMID 36243758, 2022). "NDUFS1, the gene with the most present variant (NDUFS1.1868T>G) in different samples in our cohort and not yet reported, and NDUFS2 have already been linked to cancer, mitochondrial diseases and being associated with oncogenes." (PMID 39684297, 2024). "However, recent studies discovered a role of NDUFS2 in cancer." (PMID 33923185, 2021). "For instance, HMGB1, HMGB2, and MS4A1 were hypomethylated and highly expressed, whereas hypermethylation of genes such as LDB1, NDUFS2, and POU2F2 led to their reduced expression, reinforcing the impact of DNA methylation on gene dysregulation in cancer." (PMID 40396172, 2025). "Recent studies indicate that NDUFS2 is essential for acute oxygen-sensing and hypoxic pulmonary vasoconstriction, affecting ROS and calcium signaling or could be related to cancer, since the inhibition of complex I through NDUFS2 leads to anti-cancer activity by targeting cancer energy metabolism." (PMID 38607042, 2024). "In our study, HAX1, FLAD1 and NDUFS2, which were positively correlated with DAP3, were reported to play a crucial in mitochondria which could regulate the progression in numerous cancers, indicating that DAP3 may be an important role in OXPHOS, which could affect HCC progression." (PMID 40051634, 2025).
tumor (7 papers, 2019 to 2024). "It has been shown that after interfering with the intracellular NDUFS2, the activity of Complex I is inhibited, intracellular ATP production is reduced, tumor growth is suppressed, and tumor metastasis is significantly reduced." (PMID 38195952, 2024). "Notably, BRCA patients showed a higher frequency of simultaneous mutations in MGST3, NDUFS2, and PRDX6, while co-occurring mutations were less frequent in other tumor types." (PMID 39594421, 2024). "We analyzed the expression of genes in tumor and normal samples, and the results showed that NDUFS1, NDUFS2, NDUFC1, and EPAS1 were downregulated in CRC, and SLC7A11, OXSM, LRPPRC, NDIFA11, NUBPL, and CONT1 were upregulated in CRC." (PMID 37978247, 2023). "In order to clarify which mutant is responsible for anti-tumor property of AVN A, we compared the expression of NDUFS2 and UQCRC1 in DDX3 mutant cell lines." (PMID 31391454, 2019).
infection (2 papers, 2013 to 2022). The state of being infected such as from the introduction of a foreign agent such as serum, vaccine, antigenic substance or organism. "We next tested whether there were dramatic differences in an infection model between Ndufs2+/+ and Ndufs2+/- mice." (PMID 35338200, 2022). "At 6 h post infection, the energy metabolism related genes (ATP5G2, COX17, COX5B, GSTP1, NDUFAB1 and NDUFS2) were suppressed." (PMID 23527143, 2013). "Therefore, we infected aged Ndufs2+/+ and Ndufs2+/− mice with lymphocytic choriomeningitis virus (LCMV) and measured their response to infection by percentage of epitope specific CD8 T cells that bound to GP33 tetramer one week after infection." (PMID 35338200, 2022).
NDUFS2 also shares sentences with these, for which no sentence is quoted: Alzheimer disease (3 papers); mitochondrial disease (3); optic atrophy (2); asthma (1); Ataxia (1); behavioral disorders (1); brain diseases (1); Charcot-Marie-Tooth disease (1); diabetes (1); encephalomyopathy (1); encephalopathies (1); fatty-liver (1); glioblastoma (1); Huntington disease (1); kidney damage (1); malnutrition (1); melanoma (1); metabolic disorders (1); neurological diseases (1); Optic neuropathy (1); osteosarcoma (1); retinal degeneration (1); steatosis (1); type-2 diabetes (1); viral infection (1).